BCAS3 (BCAS3 microtubule associated cell migration factor)
Diseases named in the same sentence as BCAS3 in open-access papers (continued):
Sharing a sentence is not in itself a finding about the gene and the disease.
glioma (2 papers, 2007 to 2025). A benign or malignant brain and spinal cord tumor that arises from glial cells (astrocytes, oligodendrocytes, ependymal cells). "Among the most strongly decreased candidates, we observed proteins related to DNA repair (FANCA, USP38, NET1), autophagy (BCAS3), cancer cell migration and/or invasion (RASSF2, KMO, BCAS3), as well as proteins that can be generally considered as pro-tumorigenic, particularly in glioma (KMO, BCAS3)." (PMID 39833546, 2025). "Cell lines are a more homogenous population and BCAS3 expression in glioma lines is suggestive of expression in non-vascular neuroectodermal cells." (PMID 18030336, 2007).
microcephaly (2 papers, 2021 to 2025). A congenital or acquired developmental disorder in which the circumference of the head is smaller than normal for the person's age and sex. "The patients with BCAS3 mutations presented with global growth retardation accompanied by microcephaly, short stature and seizures." (PMID 40481608, 2025). "Bcas3 KO in zebrafish caused microcephaly, reduced body length and impaired locomotor activity, consistent with the phenotypes observed in patients with BCAS3 mutations, such as severe global developmental delay, microcephaly, and short stature." (PMID 40481608, 2025). "Bcas3 knockout zebrafish exhibited early larval phenotypes resembling clinical features of patients with BCAS3 mutations, including global delayed development at early embryonic development, microcephaly and reduced body length." (PMID 40481608, 2025). "All 15 probands harboring bi-allelic variants in BCAS3 presented with a characteristic core phenotype consisting of severe global developmental delay (GDD), pyramidal tract involvement, microcephaly, and short stature." (PMID 34022130, 2021).
Alzheimer disease (1 paper, 2019). A progressive, neurodegenerative disease characterized by loss of function and death of nerve cells in several areas of the brain leading to loss of cognitive function such as memory and language. "Finally, in the broader context of traits potentially related to cognition, we find an enrichment of HHMCs in genes associated to “Alzheimer’s disease (cognitive decline)” and “Cognitive decline (age-related)”, with seven associated genes (COX7B2, BCAS3, DMXL1, LIPC, PLEKHG1, TTLL2 and VIT)." (PMID 31186485, 2019).
Anxiety (1 paper, 2025). Intense feelings of nervousness, tension, or panic often arise in response to interpersonal stresses. "Bcas3−/− zebrafish traveled shorter distances and spent less time in the top of the tank, indicating reduced exploratory behavior and increased anxiety-like behavior." (PMID 40481608, 2025).
attention deficit-hyperactivity disorder (1 paper, 2025). A disorder characterized by a marked pattern of inattention and/or hyperactivity-impulsivity that is inconsistent with developmental level and clearly interferes with functioning in at least two settings (e.g. at home and at school). "These include regions with nearest protein-coding genes such as BCAS3, RFX3, SOBP, and PEX14, mutations in which have been linked to intellectual disability, neurological deficits, attention deficit hyperactivity disorder, or autism spectrum disorders." (PMID 41279093, 2025).
colon cancer (1 paper, 2013). "One of the translocation partners of BCAS3 is BCAS4, and fusion transcripts have been detected in MCF7 and HCT116 colon cancer cells." (PMID 24019942, 2013).
developmental delay (1 paper, 2021). "Here, we establish bi-allelic BCAS3 variants as a cause of autosomal recessive syndromic global developmental delay." (PMID 34022130, 2021).
Head-Neck Squamous Cell Carcinoma (1 paper, 2023). "We used multiple databases to analyze BCAS3 expression in HNSCC using The Cancer Genome Atlas-Head-Neck Squamous Cell Carcinoma (TCGA-HNSC) dataset and validated it in oral squamous cell carcinoma (OSCC) using reverse transcription-quantitative polymerase chain reaction (RT-qPCR)." (PMID 38259392, 2023).
Hengel-Maroofian-Schols syndrome (1 paper, 2024). "This translocation completely disrupts the Dp472 muscle isoform of the DMD gene and the BCAS3 gene, which is an important cytoskeletal protein during embryogenesis, angiogenesis, and tumorigenesis, and has been recently identified to cause the autosomal, recessive Hengel–Maroofian–Schols syndrome." (PMID 39063034, 2024).
lung adenocarcinoma (1 paper, 2026). A carcinoma that arises from the lung and is characterized by the presence of malignant glandular epithelial cells. "The transcriptomic data revealed that five genes (CAMK1D, BCAS3, DNAH1, PDE10A, and C18orf63) were differentially expressed between lung adenocarcinoma patients and healthy individuals." (PMID 41868793, 2026).
medulloblastoma (1 paper, 2007). A malignant, invasive embryonal neoplasm arising from the cerebellum. "A comparative genomic hybridization analysis of medulloblastomas identified chromosomal imbalances with high-level amplifications involving 17q22-q24 and subsequent candidate gene analyses revealed amplification of RPS6KB1, APPBP2, PPM1D and BCAS3." (PMID 18030336, 2007).
Noonan syndrome (1 paper, 2020). Noonan Syndrome (NS) is characterized by short stature, typical facial dysmorphism and congenital heart defects. "These include genes related to Noonan syndrome (SOS2), sitting height (A2M), and skeletal disproportion (BCAS3), further emphasizing the need to closely evaluate skeletal phenotype when assessing a child with SS." (PMID 32939436, 2020).
Obesity (1 paper, 2021). Accumulation of substantial excess body fat. "Additionally, other causal genes are highly expressed or known to act in human brain function (i.e., NEGR1, GNPDA2, CYP46A1, DGKH) and various carcinomas (i.e., PMAIP1, HORMAD1, FES, BCAS3), indicating the potential role of metabolic dysregulation in the pathogenesis of obesity and cardiac events." (PMID 33910581, 2021).
osteosarcoma (1 paper, 2025). A usually aggressive malignant bone-forming mesenchymal neoplasm, predominantly affecting adolescents and young adults. "Furthermore, BCAS3, in conjunction with PPM1D, may be implicated in the initiation, progression, and metastasis of osteosarcoma." (PMID 40636370, 2025).
cancer (12 papers, 2012 to 2025). A tumor composed of atypical neoplastic, often pleomorphic cells that invade other tissues. "To validate the binding of the genes with these four antibodies, we examined 8 candidate genes that are involved in cancer progression, including Esr1, Bcas3, and Bard1, as well as Crebbp, Myc, Rel, Gadd45g, and Shcbp1 (not shown)." (PMID 40157910, 2025). "In this study, our initial analysis involved assessing BCAS3 expression across various cancers using online databases drawing data from the TCGA dataset." (PMID 38259392, 2023). "We observe significant BCAS3 overexpression in this tumor, aligning with its role in various cancers and indicating its significance in pathogenesis." (PMID 38259392, 2023). "BCAS3 displayed distinct expression patterns across different cancer types, with a notable emphasis on HNSCC (p<0.05)." (PMID 38259392, 2023). "Nevertheless, the precise mechanisms that drive BCAS3 involvement in cancer growth and dissemination remain elusive." (PMID 38259392, 2023). "Intriguingly, BCAS3 overexpression has been found to impede the apoptosis process, thereby reducing the sensitivity of cancer cells to chemotherapeutic drugs such as paclitaxel and doxorubicin in MCF-7 cells." (PMID 38259392, 2023). "This collective evidence strongly suggests that BCAS3 overexpression not only promotes cancer cell proliferation but also fosters resistance to chemotherapy drugs, potentially complicating treatment outcomes." (PMID 38259392, 2023). "BCAS3 and PLCSR3 were part of a second network that was highly populated with cancer related and chromatin modifying genes." (PMID 24489651, 2014). "It is crucial to identify new biomarkers for HNSCC, as there is currently no research on the involvement of the BCAS3 gene in this type of cancer." (PMID 38259392, 2023). "Some genes, e.g. BCAS3, that are fused in more than one cancer cell line retain different, non-overlapping parts of the gene in different cases, suggesting the common theme is inactivation." (PMID 23260012, 2012).
tumor (12 papers, 2007 to 2025). "While these findings offer promising avenues for further research, the underlying molecular mechanisms governing BCAS3 effects on tumor progression remain an intriguing topic for future exploration." (PMID 38259392, 2023). "The results demonstrated that BCAS3 expression was associated with histological grade (P = .004), tumour size (P = .004) and TNM stage (P < .001)." (PMID 34240781, 2021). "The expression of BCAS3 in the cells was rather random and showed a distinct association to vascular component of neoplasms of various cell lineages and inflammatory lesions." (PMID 18030336, 2007). "BCAS3 is not detected in low grade tumors indicating a temporal and spatial association of BCAS3 to highly mitotic undifferentiated tumor cells and neo-angiogenesis." (PMID 18030336, 2007). "BCAS3 (Breast Cancer Amplified Sequence 3) is a gene of unknown function on human chromosome 17q23, a region associated with breakpoints of several neoplasms." (PMID 18030336, 2007). "Furthermore, BCAS3’s association between tumor immune infiltration and autophagy was uncovered." (PMID 38259392, 2023). "According to prior surveys, MPs can downregulate specific genes in tumor cells, such as BCAS3, PHF19, and PRKCD, whose expression has been suppressed by microplastics in previous studies." (PMID 41378310, 2025). "Our study elucidates the pivotal role of BCAS3 in HNSCC by highlighting its overexpression in this tumor." (PMID 38259392, 2023). "Functional enrichment analysis suggests BCAS3's role in autophagy processes, potentially impacting tumor growth and survival dynamics." (PMID 38259392, 2023). "Our study explores BCAS3’s correlation with clinicopathological features and patient prognosis, suggesting its involvement in tumor aggressiveness." (PMID 38259392, 2023). "The link between BCAS3 expression and tumor immune infiltration is notable, indicating intricate interactions within the immune microenvironment." (PMID 38259392, 2023). "We observed a substantial increase in BCAS3 expression in OSCC tumors (n=30) compared to non-tumor tissues (n=12, p<0.05)." (PMID 38259392, 2023). "We extended our investigation to examine the relationship between BCAS3 expression and tumor immune infiltration, leveraging TIMER 2.0." (PMID 38259392, 2023). "BCAS3 is a cytoskeletal WD repeat domain-containing protein essential for angiogenesis, both during the developmental process and in tumor metastasis." (PMID 34070617, 2021). "Our analysis suggests new conserved roles for BCAS3 in tumor manifestation and progression and in tissue healing." (PMID 18030336, 2007). "As BCAS3 expression is associated with vascular precursors derived from human ES cells, it is possible that BCAS3 plays a role in the formation of tumor vessels." (PMID 18030336, 2007). "Furthermore, the impact of BCAS3 gene expression levels concerning tumor grade, stage, gender, and race in the context of HNSCC patient survival was evaluated." (PMID 38259392, 2023). "Notably, BCAS3 expression displayed a progressive increase in tandem with higher tumor grades (p<0.05)." (PMID 38259392, 2023). "Similarly, earlier research indicated the presence of BCAS3 during angiogenesis and in human embryonic stem (ES) cells, suggesting its involvement in tumor angiogenesis." (PMID 38259392, 2023). "In addition, evidence has shown a positive correlation between overexpression of BCAS3 and tumour progression." (PMID 34240781, 2021). "A tumor arising from these pericytes could be arising from progenitor mesenchymal cells, thus expressing BCAS3." (PMID 18030336, 2007). "In view of this, BCAS3 could be a surrogate marker for angiogenesis in a reparative healing process or tumor progression to higher grade of malignancy, a common phenomenon in cell biology." (PMID 18030336, 2007).
tumor (continued). "Notably, BCAS3 overexpression has been correlated with tumor development." (PMID 38259392, 2023). "Our study's insights into BCAS3 expression correlations with clinicopathological features and patient prognosis highlight its possible involvement in tumor aggressiveness and complex interactions between viral factors and tumor development in HPV-positive and HPV-negative HNSCC." (PMID 38259392, 2023). "The findings revealed a positive correlation between BCAS3 expression and B cells, CD4+ cells, and dendritic cells, while a negative correlation was observed with CD8+ cells and macrophages in the tumor immune cell infiltration of HNSCC patients (p<0.05)." (PMID 38259392, 2023). "Therefore, we speculate that high BCAS3 expression may be related to tumour malignancy." (PMID 34240781, 2021). "The function of BCAS3 is not known either in embryogenesis or during tumor progression." (PMID 18030336, 2007).
neurodevelopmental disorder (2 papers, 2021 to 2025). A behavioral and cognitive disorder with onset during the developmental period that involves impaired or aberrant development of intellectual, motor, or social functions. "Mutations in BCAS3 (BCAS3 microtubule associated cell migration factor) lead to neurodevelopmental disorders." (PMID 40481608, 2025). "In this study, we provide evidence that bi-allelic variants of BCAS3 cause a syndromic neurodevelopmental disorder." (PMID 34022130, 2021). "A similar syndromic phenotype in all probands confirmed BCAS3 loss-of-function variants as responsible for an autosomal recessive neurodevelopmental disorder." (PMID 34022130, 2021). "Here, we established BCAS3 loss-of-function variants as causative for a neurodevelopmental disorder." (PMID 34022130, 2021). "Thus, our work provides a robust and versatile model for studying the phenotypes and mechanisms of neurodevelopmental disorders caused by BCAS3 mutations." (PMID 40481608, 2025). "Mutations in BCAS3 gene are associated with syndromic neurodevelopmental disorders in humans, while the detailed pathological mechanism is still unknown." (PMID 40481608, 2025).
adenocarcinoma (1 paper, 2015). A common cancer characterized by the presence of malignant glandular cells. "For adenocarcinoma specifically, DM was observed in promoters [hypermethylated RASL12; SPTAN1, mir-26a, hypomethylated NQO1, SIRPB1, NF1A] and gene bodies [hypermethylated AKAP13, ANK family, PRKCE, ROS1; hypomethylated FAM171A1, PARK2, BCAS3, RHOJ] and many others." (PMID 26683690, 2015).
BCAS3 also shares sentences with these, for which no sentence is quoted: abscess (1 paper); Autoimmunity (1); Cognitive decline (1); diabetes (1); endometrial cancer (1); essential hypertension (1); hyperuricaemia (1); Intellectual disability (1); kidney disease (1); movement disorder (1); neurological diseases (1); oral squamous cell carcinoma (1); Parkinson’s (1); Strabismus (1); Stroke (1); type 1 diabetes (1).